RNU2-3P (RNA, U2 small nuclear 3, pseudogene)
Synonyms: U2; RNU2P1
Gene: Small nuclear RNA gene on chromosome 15 (95,745,804 to 95,745,994, forward strand). Ensembl gene ENSG00000222076.
Homologues: Orthologues: chimpanzee U2 (99% identical), macaque U2 (93% identical), rat LOC120100289 (92% identical), rat LOC120097991 (91% identical), mouse Gm26108 (87% identical), pig U2 (86% identical). Paralogues in human: U2 (93% identical), RNU2-2 (89% identical), U2 (88% identical), RNU2-4P (87% identical), RNU2-17P (86% identical), RNU2-48P (85% identical), RNU2-59P (85% identical), RNU2-52P (84% identical), RNU2-6P (84% identical), RNU2-14P (83% identical), RNU2-20P (83% identical), RNU2-25P (83% identical), and 67 more.